ELAVL4 (ELAV like RNA binding protein 4)
Description:
RNA-binding protein that is involved in the post-transcriptional regulation of mRNAs. Plays a role in the regulation of mRNA stability, alternative splicing and translation. Binds to AU-rich element (ARE) sequences in the 3' untranslated region (UTR) of target mRNAs, including GAP43, VEGF, FOS, CDKN1A and ACHE mRNA. Many of the target mRNAs are coding for RNA-binding proteins, transcription factors and proteins involved in RNA processing and/or neuronal development and function (By similarity). By binding to the mRNA 3'UTR, decreases mRNA deadenylation and thereby contributes to the stabilization of mRNA molecules and their protection from decay. Also binds to the polyadenylated (poly(A)) tail in the 3'UTR of mRNA, thereby increasing its affinity for mRNA binding. Mainly plays a role in neuron-specific RNA processing by stabilization of mRNAs such as GAP43, ACHE and mRNAs of other neuronal proteins, thereby contributing to the differentiation of neural progenitor cells, nervous system development, learning and memory mechanisms. Involved in the negative regulation of the proliferative activity of neuronal stem cells and in the positive regulation of neuronal differentiation of neural progenitor cells (By similarity). Promotes neuronal differentiation of neural stem/progenitor cells in the adult subventricular zone of the hippocampus by binding to and stabilizing SATB1 mRNA (By similarity). Binds and stabilizes MSI1 mRNA in neural stem cells (By similarity). Exhibits increased binding to ACHE mRNA during neuronal differentiation, thereby stabilizing ACHE mRNA and enhancing its expression. Protects CDKN1A mRNA from decay by binding to its 3'-UTR (By similarity). May bind to APP and BACE1 mRNAS and the BACE1AS lncRNA and enhance their stabilization. Plays a role in neurite outgrowth and in the establishment and maturation of dendritic arbors, thereby contributing to neocortical and hippocampal circuitry function (By similarity). Stabilizes GAP43 mRNA and protects it from decay during postembryonic development in the brain. By promoting the stabilization of GAP43 mRNA, plays a role in NGF-mediated neurite outgrowth (By similarity). Binds to BDNF long 3'UTR mRNA, thereby leading to its stabilization and increased dendritic translation after activation of PKC (By similarity). By increasing translation of BDNF after nerve injury, may contribute to nerve regeneration (By similarity). Acts as a stabilizing factor by binding to the 3'UTR of NOVA1 mRNA, thereby increasing its translation and enhancing its functional activity in neuron-specific splicing. Stimulates translation of mRNA in a poly(A)- and cap-dependent manner, possibly by associating with the EIF4F cap-binding complex (By similarity). May also negatively regulate translation by binding to the 5'UTR of Ins2 mRNA, thereby repressing its translation (By similarity). Upon glucose stimulation, Ins2 mRNA is released from ELAVL4 and translational inhibition is abolished (By similarity). Also plays a role in the regulation of alternative splicing. May regulate alternative splicing of CALCA pre-mRNA into Calcitonin and Calcitonin gene-related peptide 1 (CGRP) by competing with splicing regulator TIAR for binding to U-rich intronic sequences of CALCA pre-mRNA.
Synonyms: HuD; PNEM
Tractability: PROTAC: ubiquitination databases record sites on it; its protein half-life has been measured.
Gene: Protein-coding gene on chromosome 1 (50,024,029 to 50,203,772, forward strand). Ensembl gene ENSG00000162374.
Subcellular location: Cytoplasm; Perikaryon; Cell projection, dendrite; Cell projection, axon; Cell projection, growth cone
Subcellular location (Human Protein Atlas): Nucleoplasm; Vesicles
Gene Ontology:
Molecular function: mRNA 3'-UTR AU-rich region binding; mRNA 3'-UTR binding; poly(A) binding; pre-mRNA intronic pyrimidine-rich binding; protein-RNA adaptor activity; mRNA binding; nucleic acid binding; RNA binding
Biological process: 3'-UTR-mediated mRNA stabilization; positive regulation of 3'-UTR-mediated mRNA stabilization; RNA processing; mRNA processing
Cellular component: cytoplasm; axon; dendrite; perikaryon; growth cone; ribonucleoprotein complex
Genetic constraint (gnomAD): Loss-of-function variants: 1 observed, 34.65 expected, observed/expected ratio (o/e) 0.0289, 90% interval 0.009 to 0.14. The upper end of that interval is the gene's LOEUF score, 0.14, which puts it in group 1 of 6, group 1 being the genes least tolerant of losing a copy. Missense variants: 267 observed, 488.54 expected, observed/expected ratio (o/e) 0.55, 90% interval 0.49 to 0.61. Synonymous variants: 156 observed, 179.58 expected, observed/expected ratio (o/e) 0.87, 90% interval 0.76 to 0.99.
Homologues: Orthologues: chimpanzee ELAVL4 (99% identical), macaque ELAVL4 (99% identical), dog ELAVL4 (99% identical), pig ELAVL4 (99% identical), rabbit ELAVL4 (99% identical), guinea pig Elavl4 (99% identical), mouse Elavl4 (99% identical), rat Elavl4 (99% identical), tropical clawed frog elavl4 (98% identical), zebrafish elavl4 (95% identical), Caenorhabditis elegans exc-7 (53% identical). Paralogues in human: ELAVL2 (89% identical), ELAVL3 (82% identical), ELAVL1 (65% identical), RBMS3 (29% identical), RBMS1 (28% identical), RBMS2 (27% identical), PABPC1L (24% identical), PABPC1 (23% identical), SF3B4 (23% identical), SYNCRIP (23% identical), PABPC3 (22% identical), PABPC4 (22% identical), and 12 more.